KIF2A (kinesin family member 2A)
Diseases named in the same sentence as KIF2A in open-access papers (continued):
Sharing a sentence is not in itself a finding about the gene and the disease.
lymph node metastasis (5 papers, 2014 to 2023). "In a recent study, expression of KIF2A was found to be closely associated with TNM stage and lymph node metastasis in LUAD." (PMID 30813343, 2019). "We also demonstrated that patients with lymph node metastasis had a high frequency of KIF2A overexpression." (PMID 27773961, 2016). "The proportion of tumors with high KIF2A expression increased with the degree of lymph node metastasis (N0, 56.25%; N1, 65.17%; N2, 69.15%; and N3, 75.49%)." (PMID 27773961, 2016). "The fact that patients with lymph node metastasis had KIF2A overexpression in our study suggests that KIF2A overexpression correlates with an aggressive phenotype." (PMID 24950762, 2014). "We also demonstrated that patients with lymph node metastasis had high frequency of KIF2A overexpression." (PMID 24950762, 2014). "Moreover, in our results, clinicopathological analysis revealed that GC with high KIF2A expression was associated with histological type, advanced TNM stage, and lymph node metastasis." (PMID 27773961, 2016). "The high KIF2A expression was significantly correlated to histological type, TNM stage, and lymph node metastasis." (PMID 27773961, 2016). "Patients with positive lymph node metastasis had higher KIF2A expression levels than those who were negative (7.31 ± 0.66 vs 6.69 ± 0.72, P < 0.001)." (PMID 24950762, 2014). "The overexpression of KIF2A in adjacent tissues was more frequently observed in patients with lymph node metastasis than those without lymph node metastasis (6.52 ± 1.01 vs 5.91 ± 0.78, P < 0.001)." (PMID 24950762, 2014).
epilepsy (4 papers, 2016 to 2022). A brain disorder characterized by episodes of abnormally increased neuronal discharge resulting in transient episodes of sensory or motor neurological dysfunction, or psychic dysfunction. "We report that adult mice with specific deletion of KIF2A in GABAergic interneurons display abnormal behavior and increased susceptibility to epilepsy." (PMID 36733270, 2022). "Moreover, KIF2A-deficient animals showed behavioral deficits and susceptibility to epilepsy, correlating with the described human phenotype." (PMID 34404749, 2021). "They had shown that KIF2A deficient neurons have exhibited excessive axon collateral extension due to impaired microtubule depolymerization, which caused recurrent synapses as the structural basis underlying this epilepsy-like phenotype." (PMID 34404749, 2021). "Moreover, Kif2a-cKO mice and KIF2A+/H321D mice presented with behavioral deficiencies and susceptibility to epilepsy." (PMID 34404749, 2021). "If the results are reproducible in people, future work could help to diagnose and understand conditions linked to KIF2A, like schizophrenia and epilepsy." (PMID 29313800, 2018). "It would be interesting to investigate if postnatal deletion of KIF2A only in cortical interneurons could affect the maturation and connectivity of these neurons and contribute to the pathophysiological mechanism underlying epilepsy in humans." (PMID 36733270, 2022). "Our results shed light on how KIF2A deregulation triggers functional alterations in neuronal circuitries and contributes to epilepsy." (PMID 36733270, 2022). "In recent years, mouse KIF2A models have been developed, which has led to important insights concerning cortical defects and epilepsy." (PMID 34404749, 2021). "Deletion of KIF2A in cortical interneurons disrupts their migration, reduces the number inhibitory synapses, and compromises the balance between excitation and inhibition leading to epilepsy." (PMID 36733270, 2022). "Conditional deletion of KIF2A at the third postnatal week, using a tamoxifen-inducible mouse (CAGG-Cre-ERTM;Kif2aF/F), also triggers epilepsy." (PMID 36733270, 2022). "In addition, KIF2A is a causal gene in human Malformation of Cortical Development (MCD) with epilepsy, but the contribution of KIF2A to its pathogenesis is not yet understood due to the small number of human patients." (PMID 27454254, 2016).
brain malformations (3 papers, 2016 to 2024). "We suspect that additional patients with lissencephaly due to KIF2A mutation will be identified with the growing use of targeted clinical diagnostic NextGen sequencing panels for brain malformations and malformations of cortical development." (PMID 27896282, 2016). "Genetic testing included a commercial next‐generation (NextGen) sequencing panel assessing known causes of brain malformations, which revealed a heterozygous c.959C>T (p.Thr320Ile) missense mutation in KIF2A, a member of the kinesin family." (PMID 27896282, 2016). "For example, homozygous mutations in NIN and KIF2A, encoding two components of the subdistal centriolar appendage, are linked to Sickler syndrome type 7 (OMIM 614851) and a syndrome of complex brain malformations (OMIM 615411), respectively." (PMID 38300321, 2024).
cervical cancer (3 papers, 2021 to 2023). A primary or metastatic malignant neoplasm involving the cervix. "Therefore, plasma exosomal RGS18 may be more associated with cervical cancer development and progression than the other three mRNAs (KIF2A, ARL6IP5, and DAPP1)." (PMID 34827689, 2021). "TTBK2 inhibits the activity of the microtubule depolymerase of KIF2A through phosphorylation, thus promoting the migration of cervical cancer cells." (PMID 36979179, 2023). "KIF2A, an MT depolymerase, is found to be highly expressed in cervical cancer, and closely related to the prognosis of cervical cancer." (PMID 36447525, 2022). "The results of transwell experiments in this study showed that high expression of KIF2A promoted the migration and invasion of cervical cancer, and low expression of KIF2A hindered the migration and invasion of cervical cancer." (PMID 36447525, 2022). "This study found that HPV16 E6/E7 protein can up-regulate the expression of KIF2A, which can regulate the motility of cervical cancer cells." (PMID 36447525, 2022). "In summary, KIF2A plays a key role in the motility and metastasis of cervical cancer." (PMID 36447525, 2022). "In conclusion, this study confirmed the role of KIF2A in cervical cancer cell motility, and found that E6/E7 oncogenes can activate the transcription of KIF2A by activating the JNK/c-Jun signaling pathway, thereby regulating cervical cancer cell migration and invasion." (PMID 36447525, 2022). "Therefore, this study will investigate the role of KIF2A in the migration and invasion of cervical cancer cells, and the molecular mechanism of E6/E7 protein regulating the transcription and expression of KIF2A by activating the JNK signaling pathway." (PMID 36447525, 2022). "However, there is no exact experiment to verify the role of KIF2A expression in cervical cancer cell motility." (PMID 36447525, 2022).
colorectal cancer (3 papers, 2016 to 2017). A primary or metastatic malignant neoplasm that affects the colon or rectum. "It is reported that KIF2A has been investigated in a variety of cancers, including breast tumor, oral squamous carcinoma, and colorectal cancer." (PMID 26937910, 2016). "KIF2A expression in colorectal cancer exceeded that in normal adjacent tissues and negatively correlated with OS of colorectal cancer patients." (PMID 27773961, 2016).
Lissencephaly (3 papers, 2016 to 2022). A spectrum of malformations of cortical development caused by insufficient neuronal migration that subsumes the terms agyria, pachygyria and subcortical band heterotopia. "Findings support the pathogenic link between KIF2A mutation and lissencephaly, and expand the range of presentation to include infantile spasms and congenital anomalies." (PMID 27896282, 2016).
oral squamous cell carcinoma (3 papers, 2020 to 2024). "Gene knockout assays have shown that RGS12 can inhibit the progression of oral squamous cell carcinoma by controlling the polarization of M1 in TAMs by controlling ciliated MYCBP2/KIF2A signaling." (PMID 38688945, 2024).
osteosarcoma (3 papers, 2014 to 2025). A usually aggressive malignant bone-forming mesenchymal neoplasm, predominantly affecting adolescents and young adults. "Human osteosarcoma (U2OS) cells transfected with non-sense siRNA typically had bipolar spindles but 90% of cells transfected with KIF2A-specific siRNA had monopolar spindles." (PMID 24950762, 2014).
acute myeloid leukemia (2 papers, 2020 to 2022). Acute myeloid leukemia (AML) is a group of neoplasms arising from precursor cells committed to the myeloid cell-line differentiation. "This study aimed to explore the correlation of kinesin family member 2A (KIF2A) expression with disease risk, clinical characteristics, and prognosis of acute myeloid leukemia (AML), and investigate the effect of KIF2A knockdown on AML cell activities in vitro." (PMID 33331418, 2020).
allergic disease (2 papers, 2015 to 2022). An immune response that occurs following re-exposure to an innocuous antigen, and that requires the presence of existing antibodies against that antigen. "Nevertheless, our findings suggest that KIF2A might be a promising therapeutic target in allergic diseases." (PMID 35718777, 2022). "Our findings therefore provide a novel insight into the role of hypoxia in programming DCs primed Th2 responses via a KIF2A/MT1-MMP/CD44 pathway and implicate that hypoxia might be a promising therapeutic approach in allergic diseases." (PMID 26323509, 2015).
cognitive deficits (2 papers, 2021 to 2022). "Since MCDs are an important cause of developmental delay and cognitive deficits, we also examined whether kif2a−/− larvae had difficulties in acquiring, storing, and recalling learned information by performing a habituation learning assay." (PMID 34404749, 2021).
hepatocellular carcinoma (2 papers, 2019 to 2022). A malignant tumor that arises from hepatocytes. "In addition, TCGA database analyses showed that high expression of KIF2A was associated with poor prognosis in patients with renal papillary cell carcinoma and hepatocellular carcinoma." (PMID 30813343, 2019).
laryngeal squamous cell carcinoma (2 papers, 2016 to 2017). A squamous cell carcinoma that arises from the larynx. "Interestingly, a strong correlation was found between Ki67 and KIF2A expression in laryngeal squamous cell carcinoma, indicating that high KIF2A expression is closely associated with tumor aggressiveness." (PMID 28616658, 2017).
lymphoma (2 papers, 2017 to 2020). A malignant (clonal) proliferation of B- lymphocytes or T- lymphocytes which involves the lymph nodes, bone marrow and/or extranodal sites. "Molecular knockdown of KIF2A caused moderate growth inhibition in lymphoma cells (P < 0.05)." (PMID 28616658, 2017). "For example, KIF2A knockdown inhibits lymphoma cell proliferation through positively regulating PI3K/AKT signaling pathway in SCCOT Tca8113 cells." (PMID 33331418, 2020). "In our cellular transfection model of DLBCL, moderately decreased tumor cell viability was observed when KIF2A expression was silenced, suggesting that KIF2A is involved in stimulating lymphoma cell growth." (PMID 28616658, 2017). "The prevalence of elevated KIF2A expression was increased in lymphoma tissues compared with reactive hyperplasia, indicating that KIF2A may contribute to the malignant transformation of DLBCL." (PMID 28616658, 2017).
oral cancer (2 papers, 2014 to 2023). "Upregulation of RGS12 activates phosphorylation of MYCBP2 to enhance ciliogenesis by degrading KIF2A and promotes the M1 TAMs polarization to further eliminate oral cancer cells." (PMID 36797232, 2023). "To determine the role of KIF2A in TAMs, we knocked down KIF2A by transfecting KIF2A shRNAs in primary TAMs isolated from oral cancer tissue of WT mice." (PMID 36797232, 2023). "We reported that the migratory ability of KIF2A–siRNA transfected oral cancer cells decreased significantly compared to the control group." (PMID 24950762, 2014). "In this study, by investigating the roles of RGS12 on TAMs from mice with oral cancer, we revealed that RGS12 is an essential factor to control immune activation in oral cancer by regulating macrophage polarization and ciliogenesis via MYCBP2/KIF2A." (PMID 36797232, 2023).
allergic asthma (1 paper, 2022). A asthma with a basis in a pathological type I hypersensitivity reaction. "Moreover, in vivo KIF2A transfection reduced IL-33 and autophagy in the lung, leading to the attenuation of allergic asthma." (PMID 35718777, 2022). "However, the functions of KIF2A in allergic asthma remain largely elusive." (PMID 35718777, 2022).
asthma (1 paper, 2022). "However, little is known about the roles of KIF2A as well as the possible underlying mechanisms in asthma." (PMID 35718777, 2022). "To better understand the protective role of KIF2A in asthma pathogenesis, we overexpressed KIF2A in a murine model of AAI via intravenous administration of pCMV6-KIF2A using in vivo jetPEI." (PMID 35718777, 2022).
chronic gastritis (1 paper, 2016). Inflammation of the stomach that is chronic in nature. "We also examined KIF2A expression in 18 chronic gastritis, 15 intestinal metaplasia, and 37 low-grade and 62 high-grade intraepithelial neoplasias." (PMID 27773961, 2016). "We further confirmed the increased prevalence of high KIF2A expression in cancerous tissues (low- and high-grade intraepithelial neoplasia) as compared to noncancerous tissues (chronic gastritis)." (PMID 27773961, 2016).
cortical dysplasia (1 paper, 2025). "Mutations in KIF2A are associated with cortical dysplasia and early-onset neurodegeneration." (PMID 40735840, 2025).
diffuse large B-cell lymphoma (1 paper, 2017). "The aim of the present study was to investigate KIF2A expression in diffuse large B cell lymphoma (DLBCL), evaluate the association between KIF2A expression and the clinical parameters of the disease, and determine its prognostic value." (PMID 28616658, 2017).
juvenile myoclonic epilepsy (1 paper, 2018). "The progress of this line of research will allow for analysis of the pathogenesis of Kif2a-related diseases, including schizophrenia, juvenile myoclonic epilepsy, mental retardation, ocular defects, and MCD." (PMID 29313800, 2018).
malignant glioma (1 paper, 2020). A grade III or grade IV glioma arising from the central nervous system. "KIF2A knockdown suppresses cell proliferation, cell invasion, and cell migration through regulating matrix metalloproteinases-2 (MMP-2) activity in human malignant glioma cell lines." (PMID 33331418, 2020).
neuropathies (1 paper, 2023). "Identifying inhibitors that target MCAK and not Kif2A will be crucial if they are to be utilized either in combination with taxanes or as agents to give taxane-like effects without inducing neuropathies." (PMID 37444419, 2023).
ovarian epithelial tumor (1 paper, 2016). A benign, borderline, or malignant tumor that originates from the surface epithelium of the ovary. "Therefore, in this study, we aimed to determine expression levels of both HER2-neu and KIF2A protein in ovarian epithelial tumor samples and to analyze the correlation between KIF2A, HER2-neu, and other clinicopathological features in a cohort of EOC patients." (PMID 26937910, 2016).
Pachygyria (1 paper, 2020). Pachygyria is a malformation of cortical development with abnormally wide gyri with sulci 1,5-3 cm apart and abnormally thick cortex measuring more than 5 mm (radiological definition). "Pathogenic variants in DYNC1H1 and KIF2A, which encode microtubule-associated motor proteins, also lead to a spectrum of MCDs, ranging from pachygyria to dysgyria." (PMID 32895508, 2020).
Primary microcephaly (1 paper, 2019). Head circumference below 2 standard deviations below the mean for age and gender at birth. "Primary microcephaly is caused by mutations in genes encoding centrosomal proteins including WDR62 and KIF2A." (PMID 31197141, 2019).
squamous cell carcinoma of (1 paper, 2020). "Furthermore, silencing KIF2A promotes cell apoptosis via inhibiting PI3K/Akt signaling pathway in squamous cell carcinoma of the oral tongue." (PMID 33331418, 2020).
tauopathy (1 paper, 2024). Neurodegenerative disorders involving deposition of abnormal tau protein isoforms (tau proteins) in neurons and glial cells in the brain. "The present study elucidates a mechanism by which Smek1 protects against tauopathy by binding to Kif2a in neurons and thereby regulates tau phosphorylation." (PMID 39206808, 2024).
viral infection (1 paper, 2021). "Interestingly, many of the candidate proteins have only limited functional links to viral infection and immune regulation and were not previously known to interact with NAs (e.g., c8orf88, DTYMK, KIF2A, PDAP1, PDIA5, TAOK1, TAOK2, and VRK1)." (PMID 34853303, 2021).